LIF (LIF interleukin 6 family cytokine)
Diseases named in the same sentence as LIF in open-access papers (continued):
Sharing a sentence is not in itself a finding about the gene and the disease.
melanoma (continued). "Obviously, ADCYAP1R1, GPI and NTS might lead to poor prognosis for melanoma patients, while IFITM1, KIR2DL4 and LIF are more likely to improve outcomes." (PMID 38217549, 2024). "The results demonstrated that EBI3, ERAP1, and NAMPT mRNA levels were upregulated in melanoma tissues, while A2M and LIF were not insignificant." (PMID 35326741, 2022). "Angiogenic factors such as leukemia inhibitory factor (LIF), macrophage colony-stimulating factor (M-CSF), macrophage inflammatory protein-2 (MIP-2), and VEGF are highly generated by MSCs when co-cultured with melanoma B16 cells." (PMID 31130595, 2019). "Exogenous LIF was reported to act as a growth factor for melanoblasts and melanocytes, yet another study showed that LIF did not exert any growth stimulatory effect in melanoma cells." (PMID 25885043, 2015). "We found by analysis of the transcriptome of two human melanoma cell lines, WM793B (Vertical growth phase melanoma, VPG, Stage I) and WM278 (VPG, Stage II), that one particular gene, the leukemia inhibitory factor (LIF), appeared to be strongly upregulated by TGFβ." (PMID 25885043, 2015). "As LIF signaling is mediated through activation of the transcription factor STAT3, and as the p21-luc construct contains a STAT3 binding element, we next assessed whether TGFβ-induced p21 expression in melanoma was STAT3-dependent." (PMID 25885043, 2015).
Cachexia (29 papers, 2011 to 2026). Severe weight loss, wasting of muscle, loss of appetite, and general debility related to a chronic disease. "Clinically, circulating LIF levels tend to be elevated in patients with advanced malignancies, and are thought to be a major contributor to cachexia-related weight loss and anorexia." (PMID 40869331, 2025). "For example, many human and murine tumor lines (including pancreatic, lung, and colon cancers) secrete LIF, and high LIF levels are associated with cachexia development in tumor-bearing mice." (PMID 40869331, 2025). "To investigate the contribution of LIF-induced functional and metabolic changes in the liver to cachexia, we generated a mouse line with a conditional LIF knock-in allele and a conditional LIFR knockout allele (TgL/LIFRflox/flox)." (PMID 38245529, 2024). "Several human and mouse cancer cell lines, including mouse colorectal carcinoma cell line C26, secrete LIF, which is associated with cachexia development in tumor-bearing mice." (PMID 38245529, 2024). "Overall, the available studies have confirmed that LIF can lead to weight loss through skeletal muscle atrophy, fat loss, and anorexia nervosa, which contributes to the progression of cachexia." (PMID 35740622, 2022). "The CRISPR-Cas9 knockout of LIF within this model resulted in significantly decreased loss of body weight, muscle, and fat, further proving the significance of LIF in causing cachexia." (PMID 35204717, 2022). "Cytokines have been investigated as potential causes of cancer cachexia for nearly three decades, and although cachexia is likely unable to ever be attributed to one single cytokine, LIF is considered a major contributing factor to causing cachexia." (PMID 35204717, 2022). "The absolute serum concentrations of IL-6 and LIF observed during RM9-associated cancer cachexia were 83 ± 20 ng/mL and 3.4 ± 0.8 ng/ml, respectively." (PMID 35785158, 2022). "In nude mice that have been inoculated with the neuroepithelioma cell line NAGAI, large amounts of LIF are also detected in association with the induction of cachexia." (PMID 35740622, 2022). "LIF has recently been shown to be implicated in cachexia-associated lipolysis as well, whereby interaction between this interleukin and its cognate membrane receptor LIFR-α caused enhanced expression of genes involved in lipids catabolism." (PMID 32195193, 2020). "To clarify the mechanism underlying the difference in the cachexia-inducing ability of these cells, we conducted DNA microarray analysis, focusing on cell proliferation and the production of leukemia inhibitory factor (LIF), a cachexia-inducing factor." (PMID 30410674, 2018). "In our previous study, we suggested that human LIF is a causative factor in the 85As2-induced cachexia model." (PMID 30410674, 2018). "While the connection of LIF with cachexia has been established, the underlying mechanisms whereby LIF promotes cachexia remain unclear." (PMID 38245529, 2024). "In addition, the progression of anorexia in cachexia caused by LIF is partly influenced by leptin, which is a crucial adipokine, and changes in the adipose tissue or bodyweight can affect the leptin secretion." (PMID 35740622, 2022). "Thereby, LIF impacts energy metabolism and shifts it towards weight loss and cachexia phenotypes." (PMID 35204717, 2022). "Pharmacological activation of PPARα with the agonist fenofibrate restores hepatic lipid homeostasis and mitigates LIF-induced cachexia, underscoring the importance of isoform-specific regulation in maintaining metabolic integrity." (PMID 41476922, 2025). "This appears to be consistent with previous data showing that LIF is able to induce an acute-phase response and cachexia." (PMID 40243929, 2025). "Other IL-6 family cytokines, including oncostatin M (OSM) and leukemia inhibitory factor (LIF), also contribute to cachexia through STAT3 activation." (PMID 40704145, 2025).
Cachexia (continued). "Previous studies have shown that mice bearing C26 tumors develop cachexia, and it has been suggested that the elevated LIF levels produced by C26 tumors contribute to cachexia in the tumor-bearing mice." (PMID 38245529, 2024). "Characterizing the metabolic changes in mice during cachexia development revealed decreased hepatic de novo lipogenesis and disrupted lipid homeostasis induced by LIF overexpression in mice." (PMID 38245529, 2024). "Activating PPARα by fenofibrate, a PPARα agonist, restores lipid homeostasis in the liver and inhibits LIF-induced cachexia." (PMID 38245529, 2024). "Liver-specific LIF receptor knockout attenuates LIF-induced cachexia, suggesting that LIF-induced functional changes in the liver contribute to cachexia." (PMID 38245529, 2024). "Results from this study showed that hepatic de novo lipogenesis was significantly inhibited during cachexia development in TAM-injected TgLC mice with LIF overexpression." (PMID 38245529, 2024). "Activating PPARα by the fenofibrate diet significantly increased the expression of PPARα target genes, restored lipid homeostasis in the liver, and more importantly, significantly inhibited LIF overexpression-induced cachexia." (PMID 38245529, 2024). "Leukemia inhibitory factor (LIF), a multi-functional cytokine, has been suggested as a cachexia-inducing factor." (PMID 38245529, 2024). "In this study, we established an inducible transgenic LIF overexpression mouse model (TgLC) which allows us to characterize the effect of systemic LIF elevation on cachexia." (PMID 38245529, 2024). "Blocking the LIF signaling in the liver or re-activating PPARα inhibits LIF overexpression-induced cachexia in mice." (PMID 38245529, 2024). "In a transgenic mouse model with conditional LIF expression, systemic elevation of LIF induces cachexia." (PMID 38245529, 2024). "Taken together, these results demonstrate that the systemic elevation of LIF levels induces cachexia in mice." (PMID 38245529, 2024). "In summary, we established a transgenic LIF overexpression mouse model that robustly induces cachexia." (PMID 38245529, 2024). "Activating PPARα by feeding mice with the diet containing PPARα agonist fenofibrate restored lipid homeostasis in the liver and significantly inhibited cachexia induced by LIF overexpression." (PMID 38245529, 2024). "In TgLC mice with LIF overexpression, disrupted lipid homeostasis was observed during cachexia development." (PMID 38245529, 2024). "Our cachexia classification was validated by the increase of CIFs genes in the tumor of LM patients, such as LIF, IL6, IFNG, and CCL2." (PMID 36774484, 2023). "The separate stimulation of TNF and IL-1β promoted the secretion of LIF and IL-6 in a cachexia study with tumor-bearing mice, resulting in a synergistic effect." (PMID 35740622, 2022). "Unfortunately, there is little research on LIF in this immunotherapy for cachexia, and more in-depth studies can provide more methods for treating cachexia." (PMID 35740622, 2022). "At present, histone deacetylation inhibitor AR-42 has been observed to impede muscle atrophy by blocking multiple pro-cachexia drivers, including LIF, to ameliorate cachexia." (PMID 35740622, 2022). "LIF plays a broad role in cachexia, so we believe that targeted LIF has excellent potential for treating cachexia." (PMID 35740622, 2022). "Thena, an anaplastic thyroid cancer cell, induces cachexia in mice by expressing higher levels of IL-6, LIF, and TGF-β." (PMID 35740622, 2022). "For instance, LIF is known for its strong cachexia-inducing ability in animal models, whereas it is also associated with cancer-related fatigue and weight loss in humans." (PMID 36028644, 2022). "Proinflammatory cytokines such as IL-6, TNF-α, and LIF have been identified to lead to muscle wasting in cachexia." (PMID 35740622, 2022). "Intriguingly, increasing studies have confirmed that LIF contributes to the progression of cachexia, especially in patients with metastatic tumors." (PMID 35740622, 2022).
Cachexia (continued). "Noncoding RNAs such as circPTK2, infection, and cytokines such as LIF contribute to lipolysis in cachexia." (PMID 35740622, 2022). "Weight maintenance is the ultimate goal in the treatment of cachexia; therefore, we need to consider the therapeutic potential of LIF in cachexia in a holistic manner." (PMID 35740622, 2022). "Available experiments have demonstrated that elevated plasma LIF concentrations are associated with lipolytic enzymes, such as in murine cachexia models bearing SEK1 and NAGAI cells, and that a reduction in LPL activity caused by LIF can regulate lipolysis." (PMID 35740622, 2022). "Considering the complex mechanisms in cachexia, we also focus on the interactions between LIF and other key cytokines in cachexia and existing therapeutics targeting LIF." (PMID 35740622, 2022). "We and others have shown that murine cancer cachexia models have elevated serum levels of IL-6 and LIF, which contribute to adipose wasting in this syndrome." (PMID 35785158, 2022). "LIF has long been known to have an impact on adipocyte lipolysis which is a cornerstone of cancer related cachexia." (PMID 33630157, 2021). "The same research group demonstrated that LIF is the dominating cachexia initiating factor for C26 tumors in vivo." (PMID 33557173, 2021). "The current study established in vitro and in vivo LLC cachexia models and the findings showed higher LIF protein and mRNA expression levels in gastrocnemius and C2C12 of LLC group compared with control." (PMID 34838029, 2021). "A recent study further demonstrated the involvement of tumor-secreted LIF in myotube atrophy in a C26 cancer-induced cachexia model." (PMID 32195193, 2020). "Several of these upstream regulators such as IL-1 alpha, IL4, IL6, LIF, TNF have known causal roles in cachexia validated using experimental models." (PMID 33334063, 2020). "TLR5 stimulation promoted LIF production, suggesting that this mechanism contributes to activation of the cachexia-inducing ability of 85As2 cells." (PMID 30410674, 2018). "LIF concentration in the plasma was increased by activation of the TLR5 signaling pathway; this suggests that LIF production contributes at least partially to activating the cachexia-inducing ability of 85As2 cells." (PMID 30410674, 2018). "LIF is a tumor-derived factor that is involved in the development of cachexia/anorexia, alongside IL-6 and TNFα." (PMID 30513935, 2018). "Our previous study suggested that LIF contributes to inducing cachexia in 85As2-induced cachexia model rats." (PMID 30410674, 2018). "In the case of cancer cachexia, LIF acts in concert with a number of other catabolic factors (IL-6, TNF-α, GDF15, etc.)that may amplify signals of muscle-wasting." (PMID 40869331, 2025). "To further investigate the contribution of impaired lipid metabolism in the liver to cachexia induced by LIF overexpression, we tested whether fenofibrate inhibits cachexia development in both TgLC and C26 tumor-bearing mice." (PMID 38245529, 2024). "Systemic elevation of the LIF levels quickly induced cachexia in TgLC mice." (PMID 38245529, 2024). "However, most cancer cachexia mouse models are unable to distinguish the contribution of LIF to cachexia through cell-intrinsic mechanisms or the systemic effects to the host." (PMID 38245529, 2024). "While this study reveals the LIF-induced functional and metabolic changes in the liver and its contribution to cachexia, further studies are needed to understand the role of LIF in additional organs, the signaling pathway(s) that mediate the role of LIF, and its contribution to cachexia." (PMID 38245529, 2024). "Collectively, these results demonstrate that fenofibrate activates PPARα and its downstream targets involved in lipogenesis in the liver to ameliorate the impaired lipid metabolism induced by LIF overexpression in TgLC mice and C26 tumor-bearing mice, which in turn inhibits cachexia development." (PMID 38245529, 2024).
Cachexia (continued). "The C26 tumor-induced cachexia model cannot differentiate the contribution of the direct effect of LIF secreted from tumor cells on cachexia from the secondary effects of LIF in promoting the growth, proliferation and nutritional needs of tumor cells on cachexia." (PMID 38245529, 2024). "The decreased circulating leptin is an important “natural” systemic response to combat LIF-induced cachexia and therefore may also be important for the mechanisms of potential cachexia therapies." (PMID 35740622, 2022). "We speculate that the effect of neuropeptides may be the self-regulation of the body in response to the anorexia or cachexia effect produced by LIF." (PMID 35740622, 2022). "In addition, because cachexia is a systemic disease, elevated serum LIF is seen as an indicator of poor prognosis for cancer patients, further demonstrating its potential key role in this pathological process." (PMID 35740622, 2022). "However, a more thorough study of LIF and therapeutic drugs in cachexia would definitely complement current treatments." (PMID 35740622, 2022). "In fact, these failures may be explained in light of the fact that another cytokine, the leukemia inhibitory factor (LIF), has been shown to be involved in cancer cachexia at least in rodent models and to be dominant over IL-6." (PMID 36078078, 2022). "In some cases, LIF has been thought to be a factor in the origin of cachexia." (PMID 35740622, 2022). "Studies investigating pathways involved in the onset of cachexia found several cytokines, such as TNFα, IL-1, IL-6 and LIF, which might play an important role as biomarkers or targets for tailored treatment." (PMID 36078078, 2022). "High miR-29c levels can ameliorate the lung cachectic phenotype and directly regulate LIF protein expression, therefore, the current study hypothesized that LIF expression is correlated with cachexia." (PMID 34838029, 2021). "Our data suggest that only LIF contributes to cachexia onset caused by 85As2 cells, with no contribution by other IL-6 family cytokines." (PMID 30410674, 2018). "The increase in LIF production resulting from activation of the TLR5 signaling pathway may contribute to the cachexia-inducing ability of 85As2 cells." (PMID 30410674, 2018). "Plasma LIF concentration after 4 weeks was inversely correlated with both muscle mass (R2 = 0.7311) and food intake (R2 = 0.7557), suggesting the higher LIF levels correlated with the severity of cachexia." (PMID 30410674, 2018). "Thereafter, a number of studies explored the hypothalamic actions of LIF in cachexia." (PMID 28865476, 2017). "Only in 1999 was it proposed that the involvement of LIF in the regulation of hypothalamic neurotransmitters could mediate its cachexia-inducing effects." (PMID 28865476, 2017). "Our results demonstrate that LIF overexpression downregulates PPARα expression and its target genes involved in lipogenesis, which suggest that LIF overexpression may decrease lipogenesis and disrupt lipid homeostasis in the liver, thereby inducing cachexia." (PMID 38245529, 2024). "Further investigations with mouse models of cachexia revealed that administration of recombinant LIF could induce a short-term decrease in body weight and adipose tissue, plus a transient loss of appetite, which was compensated for in these animals by reduced leptin levels." (PMID 35204717, 2022). "LIF promotes hepatic metabolic dysfunction via STAT3, and liver-specific deletion of the LIF receptor ameliorates cachexia-related lipid abnormalities." (PMID 40704145, 2025). "Here, the authors show that overexpression of leukemia inhibitory factor (LIF), a secreted cytokine, suppresses de novo lipogenesis and induces cachexia in mice." (PMID 38245529, 2024). "Previous studies have identified several cachexia-related cytokines, including interleukin-6 (IL-6), tumor necrosis factor alpha (TNF-α), IL-1β, and the leukemia inhibitory factor (LIF)." (PMID 35740622, 2022).